JRK (Jrk helix-turn-helix protein)
Description:
May bind DNA.
Synonyms: JH8; jerky
Tractability: PROTAC: ubiquitination databases record sites on it.
Gene: Protein-coding gene on chromosome 8 (142,657,460 to 142,681,968, reverse strand). Ensembl gene ENSG00000234616.
Subcellular location: Nucleus
Subcellular location (Human Protein Atlas): Nucleoli; Nucleoplasm; Nuclear bodies
Gene Ontology:
Molecular function: protein binding; DNA binding; mRNA binding; nucleic acid binding
Biological process: positive regulation of canonical Wnt signaling pathway
Cellular component: nucleus; cytoplasm; ribonucleoprotein complex
Genetic constraint (gnomAD): Loss-of-function variants: 1 observed, 0.77 expected, observed/expected ratio (o/e) 1.3, 90% interval 0.3 to 1.91. That is too few expected variants to judge how well the gene tolerates losing a copy. Missense variants: 242 observed, 219.35 expected, observed/expected ratio (o/e) 1.1, 90% interval 0.99 to 1.23. Synonymous variants: 95 observed, 90.59 expected, observed/expected ratio (o/e) 1.05, 90% interval 0.89 to 1.24.
Homologues: Orthologues: chimpanzee JRK (92% identical), macaque JRK (89% identical), rat Jrk (78% identical), mouse Jrk (77% identical), guinea pig JRK (75% identical), dog JRK (74% identical), pig JRK (69% identical), tropical clawed frog tigd3 (14% identical). Paralogues in human: JRKL (32% identical), TIGD2 (30% identical), TIGD7 (26% identical), TIGD1 (23% identical), TIGD5 (23% identical), TIGD4 (21% identical), CENPB (20% identical), TIGD6 (18% identical), TIGD3 (17% identical), POGZ (15% identical), POGK (14% identical).
Diseases named in the same sentence as JRK in open-access papers:
JRK is named in the same sentence as 10 diseases in open-access papers, as found by Europe PMC text mining. Sharing a sentence is not in itself a finding about the gene and the disease. The quoted sentences say what the papers report.
ovarian carcinoma (2 papers, 2022 to 2025). A malignant neoplasm originating from the surface ovarian epithelium. "JRK is a positive regulator of β-catenin transcriptional activity and is overexpressed in colon, breast, and ovarian cancer." (PMID 40358182, 2025). "For instance, high expression of POGZ is reportedly associated with a poor prognosis of osteosarcoma, while JRK expression was aberrantly elevated in colorectal, breast, and ovarian cancers." (PMID 36421335, 2022).
autism (1 paper, 2020). Persistent deficits in social interaction and communication and interaction as well as a markedly restricted repertoire of activity and interest as well as repetitive patterns of behavior. "It has been demonstrated that disruptions of POGZ are associated with autism, while inactivation of JRK in mice result in epileptic seizures, and JRK was found to be overexpressed in cancers." (PMID 32742312, 2020).
sarcoma (1 paper, 2022). A usually aggressive malignant neoplasm of the soft tissue or bone. "Notably, in a sarcoma study, it was found that a four-gene signature, including DHRS3, JRK, TARDBP, and TTC3, can predict patient survival based on a real-world cohort." (PMID 36231133, 2022).
soft tissue sarcoma (1 paper, 2022). A malignant neoplasm arising from muscle tissue, adipose tissue, blood vessels, fibrous tissue, or other supportive tissues excluding the bones. "In addition, JRK expression predicts worse survival in soft tissue sarcomas." (PMID 36421335, 2022).
cancer (3 papers, 2020 to 2023). A tumor composed of atypical neoplastic, often pleomorphic cells that invade other tissues. "In conclusion, in this study, we highlighted the role, and the associated molecular mechanisms of JRK solution in cancer treatment, by mainly focusing on apoptotic mechanisms in EAC-bearing BALB/c mice." (PMID 33680036, 2020). "Third, evening chronotype has been associated with DNA methylation of certain gene sites, like BACH2, JRK and RPS6KA2, which are related to the cancer development." (PMID 36093575, 2023). "JRK activates apoptotic pathway and inhibits anti-apoptotic genes and proteins in Ehrlich ascites carcinoma- bearing BALB/c mice that could be beneficial in cancer treatment." (PMID 33680036, 2020).
JRK also shares sentences with these, for which no sentence is quoted: breast tumors (1 paper); colorectal tumors (1); lung carcinoma (1); osteosarcoma (1); prostate carcinoma (1).